CCL21 (C-C motif chemokine ligand 21)
Diseases named in the same sentence as CCL21 in open-access papers (continued):
Sharing a sentence is not in itself a finding about the gene and the disease.
tumor (continued). "We observed a significant reduction in the chemokine CCL21, also referred to as secondary lymphoid tissue chemokine (SLC) and the ligand for CCR7-expressing cells, within E2-/- compared to control B6 lungs, both at homeostasis and after tumor seeding." (PMID 37426658, 2023). "We obtained five cell subpopulations, including four clusters (C0, C1, C2, C4) of tumor endothelial cells (PLVAP, VWA1, HSPG2, and INSR) and lymphatic endothelial cells (C3) (PDPN, CCL21)." (PMID 37715019, 2023). "Studies have shown that EV-packaged CCR7-induced tumor cells recognizes and accumulates toward lymphogenic CCL19 and CCL21, thereby promoting preferential tumor cell localization in sentinel LNs1." (PMID 36971125, 2023). "It has been reported that the CCL19/CCL21/CCR7 axis functions in immune cells and helps cells migrate to SLOs or other tumor sites and activate the host cell response." (PMID 34689225, 2022). "In both models, tumoral overexpression of CCL3, CCL19, CCL21, and XCL1 significantly repressed tumor growth, despite the differential overexpression levels in these cell lines." (PMID 36654820, 2022). "Vaccination with Ad-CCL21-DC induced systemic Ag-specific immune responses and enhanced infiltration of CD8+ T cells into the tumor site." (PMID 35806328, 2022). "Most TSGs including the essential chemokines for the formation of TLSs such as CXCL13 and CCL21 showed greater frequency of CNV gain, which indicated the neogenesis of TLSs in tumor tissue." (PMID 36420257, 2022). "Introduction of exogenous genes into tumor cells by recombinant plasmid techniques (e.g., lentiviral transfection) is another way to achieve elevated concentrations of CCL19/CCL21 protein." (PMID 35702353, 2022). "In both CT26 and MC38 tumor models of our study, CCL19 and CCL21 showed powerful anti-tumor activities, with CCL19 being more potent than CCL21, although the overexpression levels varied in the two tumor cell lines." (PMID 36654820, 2022). "In contrast to the controls, the protein expressions of CXCR4, CXCL12, CCR7, CCL21, P-ERK1/2, MMP-9, and MMP-2 in SK-Hep1 cells were significantly increased after transfection of tumor-derived DNA, while the increase was reversed by sinobine hydrochloride." (PMID 35860597, 2022). "The CCL21-CCR7 axis has also been shown to be an important lymphatic regulator of metastasis; tumor expression of CCR7 increases lymph node metastasis in mouse models, while neutralization of the CCR7 ligand CCL21 in lymphatics decreases lymph node metastasis." (PMID 35216243, 2022). "For BCC, studies have revealed the presence of high concentration of T-regs, not only in TME, but also in the tumor bordering skin, chemoattracted by different chemokines, for example CC chemokine ligand 17, 18 and 21 (CCL17, CCL18 e CCL21)." (PMID 35775005, 2022). "The blockade of JNK and p38, a downstream signal of CCL21/CCR7, in PTX-treated tumour cells resulted in a decreased migration of tumour cells." (PMID 35280672, 2022). "Tumoral overexpression of CCL19, CCL21, and XCL1 significantly increased ratios of total cDCs, cDC1, and cDC2 subtypes among CD45+ leukocytes in the TME, as compared to the empty vector control tumors." (PMID 36654820, 2022). "When the chemokine CCL21 and IL7 was transduced into CAR-T cells, it significantly improved survival and infiltration of both CAR-T and dendritic cells in the tumor, leading to complete tumor remission." (PMID 35432319, 2022). "Further differential and pathway analysis revealed remodeling of endothelial cells in AML, including high expression of C-C Motif Chemokine Ligand 21 (CCL21), TBX1 and NRP2 specifically observed in tumor LECs." (PMID 36028490, 2022). "After anti-HER2 treatment, for the tumor with HER2 amplification, the release of cytokines such as CCL2, CCL21, VEGF, and CXCL1 was downregulated, and the immunosuppressive factors of the tumor microenvironment were improved." (PMID 36211361, 2022).
tumor (continued). "Fluorescence-activated cell sorting (FACS) analysis showed that CCL19, CCL21, and XCL1 boosted the ratios of DCs and T cells in CD45+ leukocytes while CCL3 increased the percentage of CD45+ leukocytes in total cells in MC38 tumor." (PMID 36654820, 2022). "Tumor samples expressed VECF-C, -D and -R3, as well as CXCL12, CCL21 and CXCR4 with the highest lymphatic vessel density at the invasive tumor edges." (PMID 35163401, 2022). "In mouse CRC models, we demonstrated that all four chemokines, including CCL3, CCL19, CCL21, and XCL1, effectively inhibited tumor growth." (PMID 36654820, 2022). "The cells residing in TLS in tumours are known to express Th1, CD4, CD8, CD31, CD23, FOXP3, chemokines (CCL19, CCL21) and clusters of DC-Lamp+ mature dendritic cells providing an immune-supportive niche." (PMID 35355992, 2022). "In addition, our study revealed that MXRA8 expression correlated with the expression of multiple metastasis-associated chemokines (CXCL12, CXCL13, CCL9, CCL21, CXCR4, CXCR5, and CCR7), suggesting that MXRA8 may be involved in tumor invasion and metastasis by regulating the secretion of chemokines." (PMID 36703779, 2022). "Upregulation of the CCL21/CCR7 axis results in the migration of tumour cells from primary to lymphatic vessels, promoting lymphatic metastasis of various tumours." (PMID 35280672, 2022). "As revealed by WB analyses, the expression of CXCL12, CXCR4, CCL21, and CCR7 proteins in SK-Hep1 cells was significantly increased after transfection with tumor-derived DNA in contrast to the blank control group." (PMID 35860597, 2022). "Whereas overexpression of CCL21 triggered an increase in tumor size, while under-expressed MALAT1-1 or MALAT1-2 diminished the tumor volume (p < 0.05)." (PMID 34001131, 2021). "Patients with low PD-L1 levels displayed a strong trend towards an impaired prognosis, and circulating PD-L1 was negatively correlated with experimental markers of promalignant tumor characteristics such as CCL1, CCL21, CCL25 and CCL26." (PMID 34207359, 2021). "Hallmarks of a gradual dedifferentiation of HECs correlating with tumor progression included reduced expression of PNAd, ICAM-1, CCL21, and the ectoenzyme ATX." (PMID 34706240, 2021). "Compared with those in the normal pancreas (GTEx + TCGA), CA9, TNNT1, CCL21, LY86, and CCL19 were all expressed higher in tumor tissues, except for FABP4, which was expressed lower in a tumor (p < 0.001)." (PMID 34777388, 2021). "Several of these chemokines, including CCL21, CCL2, and CCL4, recruit anti-tumor leukocytes but can also recruit pro-tumor leukocytes such as Tregs, depending on the type of malignancy." (PMID 34316327, 2021). "Highly invasive cancer cell line (MDA-MB-231) presented the similar enhanced invasion following CCL21 expression, indirectly confirming the commonality of the CCL21-CCR7 axis on the enhanced caner malignancy under the tumor microenvironment." (PMID 34671596, 2021). "We confirmed the control of the main chemokine/receptor axes, CXCL12/CXCR463 and CCL21/CCR7,11, 64 involved in tumour escape and verified their dependency on hypoxia." (PMID 33624446, 2021). "This increases their homing behaviour and drives tumor growth and metastasis, particularly towards lymphatic organs, where the two ligands of CCR7, CCL19 and CCL21, are constitutively expressed." (PMID 34575965, 2021). "CXCL13 expressed by follicular DCs facilitates B cells into tumor and formation of germinal center, while CCL19 and CCL21 are crucial for recruitment of T cells and DCs, favoring lymphoid neogenesis." (PMID 34122408, 2021). "In vivo studies revealed that metastatic tumour formation is decreased when CCL21 expression is knocked down in secondary lymphoid organs, since this diminishes both the chemotactic and antiapoptotic effects of CCR7-expressing tumour cells." (PMID 34298676, 2021).
tumor (continued). "Either integrin-α9β1 or TNC antibodies reduce CCL21 mRNA and protein expression to improve hypoimmunity, suggesting that blocking integrin-α9β1 or TNC can alter the SCC tumour microenvironment." (PMID 33790909, 2021). "The intra-tumoral administration of CCL21 or CCL19 ligands induces increased intratumoral influx of DCs and T cells, ultimately, reducing tumor growth and prolonging the survival of tumor-bearing mice." (PMID 34361107, 2021). "VEGFC can upregulate the expression of CCL21 in lymphatic vessels, driving tumor cells to express CCR7, and enhance the invasive phenotype of tumor cells." (PMID 34552874, 2021). "After the development of a CCL21-specific backbone, the addition of a link to GAG-mimicking molecules can be considered to impair some CCL21-specific tumour-promoting effects." (PMID 34060588, 2021). "Intratumoral Ad-CCL21-DC vaccination resulted in induction of systemic tumor-specific immune responses, enhanced tumor CD8+ T-cell infiltration, and increased tumor programmed death-ligand 1 expression." (PMID 34806054, 2021). "DC activity following monotherapy with CCL21-DC tumor lysate presented MHC Class I (3-fold) and MHC Class II (3-fold) to tumor vaccine specific T cells." (PMID 32570793, 2020). "However, the molecular mechanisms by which CCL21 regulates tumor immunity remain largely unknown." (PMID 29687228, 2020). "An active mechanism of tumor dissemination via lymphatics involves the chemokines CCL21 and CCL19, which are secreted by tumor cells." (PMID 33262763, 2020). "In comparison to diluent control or monotherapy, anti-PD-1 plus CCL21-DC tumor lysate Ag induced the highest DC activity of presenting MHC Class I (27-fold) and MHC Class II (36-fold) K-RasG12D tumor peptides to tumor-vaccine-specific T cells." (PMID 32570793, 2020). "Increased expression of CCL19 and CCL21 in a tumor results in anti-cancer TIL infiltration and an improved prognosis for many tumor patients." (PMID 33076281, 2020). "For example, a low level of CCL21 expressed in LAMP3+ DCs hinders CCR7+ cells, which facilitates tumor growth and indicates an unfavorable prognosis for HCC patients." (PMID 33225985, 2020). "Similarly, CCL21, which has been described to enhance the recruitment of immune cells in the tumor and to participate to the establishment of a potent immune cellular response, is significantly reduced in the tumor microenvironment compared to the adjacent tissue." (PMID 31105699, 2019). "We also investigated the presence of CXCL12, CCL21, CXCL11, IP-10 (or CXCL10), CCL19, and CCL27, which participate to the recruitment of specific NK cell populations to the tumor site." (PMID 31105699, 2019). "Positive correlations were found between CDK12 expression and number of CD8+ cells in tumor tissues, as well as between CDK12 and CCL21 mRNA expression." (PMID 31523177, 2019). "Administration of antibody-guided LIGHT activated lymphotoxin-beta receptor signaling which, in turn, facilitated production of chemokines CCL21 and CXCL13 that recruited T cells into the tumor." (PMID 30873179, 2019). "The high expression of CCL19 and CCL21 in TIL-rich cancers suggests that these chemokines play important roles in attracting T cells, NK cells and mature dendritic cells into the tumor tissues." (PMID 30967156, 2019). "VEGF-C has been shown to upregulate CCL21 expression by LECs, driving CCR7-dependent tumor chemoinvasion toward lymphatic vessels." (PMID 31105685, 2019). "The secretion of CCL21 by LECs, which drives CCR7-dependent tumor migration through LVs, is also enhanced in response to VEGF-C." (PMID 31024552, 2019). "Our in vivo findings correlated with those found in vitro and show that OT-I T-cells pre-cultured on substrate-immobilized CCL21 + ICAM1, suppressed tumor growth to a significantly greater extent than those pre-cultured on an uncoated substrate." (PMID 29942308, 2018). "CCL21 is expressed in secondary lymphoid organs, binds to CCR7 and facilitates lymphatic invasion of tumor cells." (PMID 30018456, 2018).
tumor (continued). "While the enhanced cytotoxicity of T-cells cultured on CCL21 + ICAM1 toward cultured cancer cells was compelling, we further tested their capacity to kill tumor cells in vivo." (PMID 29942308, 2018). "VEGF-C and lymphatic flow both upregulate CCL21 in lymphatic endothelium, attracting CCR7+ tumor cells." (PMID 29527513, 2018). "In conclusion, we showed that pre-culturing CD8+ T-cells on substrate-immobilized CCL21 + ICAM1 increases both the proliferation of T-cells and their tumor-killing capacity, leading to enhanced tumor suppression abilities." (PMID 29942308, 2018). "We observed that the mRNA expression of CCL5 and CCR5 as well as LTβR-related chemokines, such as CCL21, CCL19 and CXCL13 were substantially enhanced in the tumor tissue of EL4-Axl-bearing mice compared with mock control." (PMID 28423548, 2017). "Several cytokines, such as CCL2, CCL21, VEGF and CXCL1 are present at high levels in the tumor microenvironment and known to be involved in tumor growth promotion, vascular development, and evasion of antitumor immunity." (PMID 28969039, 2017). "Lymphocytes also release cytokines and chemokines, such as IL-16, CCL21, and VEGFA, that attract monocytes, dendritic cells (DCs), and endothelial cells to the tumor core and invasive margin." (PMID 27129159, 2016). "CCR7 expression on tumor cells promotes lymphatic spread in several malignant tumors, although a comprehensive characterization of the CCR7-CCL19/CCL21 axis in LN metastasis still remains to be determined." (PMID 28036019, 2016). "Tumor cells are guided into the lymphatics by chemokine gradients, in which CCL19 and CCL21 are key players in metastatic dissemination of malignant cells via the lymphatic system." (PMID 28036019, 2016). "In studies which correlate CCL21 and CCR7 expression, not only the expression level but also the source, tumor cells versus infiltrating immune cells, should also be considered and recorded." (PMID 27369431, 2016). "Intranodal lymphatic sinuses are also greatly influenced by CCR7-CCL19/CCL21, CXCL12/CXCR4, S1P, IL-7, IFN-γ, integrin α4β1, and TGF-β in tumor microenvironment." (PMID 28036019, 2016). "Tumor-infiltrating CD8+ T cells and NK cells were also shown to drive the de novo development of PNAd+ TNFRI+ CCL21+ HEV-like blood vessels through the production of LT and IFN-γ." (PMID 27752258, 2016). "C-C chemokine receptor 7 (CCR7) expression levels, the marker of migrating DCs, in spleen DCs and tumor drLN and its ligands C-C motif ligand 19 (CCL19) and CCL21 in spleen were substantially increased by ascophyllan." (PMID 27008707, 2016). "HPV-positive tumor tissue-derived cell cultures produced markedly higher levels of chemokines, namely CXCL9, CXCL10, CXCL12, CCL17 and CCL21, and slightly higher levels of the cytokines IL-2, IL-17, IL-23 and IFNγ." (PMID 25949860, 2015). "Research has revealed that the Akt and ERK pathways are involved in the CCR7-induced migration of tumor cells, and we also detected increased activation of ERK1/2 and p-Akt in KYSE410 and Eca9706 cells after treatment with CCL21." (PMID 26667143, 2015). "In vivo studies revealed that metastatic tumor formation is decreased when CCL21 expression is knocked down in secondary lymphoid organs, since this diminishes both the chemotactic and antiapoptotic effects of CCR7-expressing tumor cells." (PMID 25744065, 2015). "At first, quantitative real-time PCR was employed to compare the expression profile of CCR7, CCL21, and VEGF-C in primary tumor and adjacent breast tissues (control)." (PMID 25744065, 2015). "While exogenous CCL21 has stimulated VEGF-C production by parental cells, the secretion level of VEGF-C from CCR7 shRNA transfected tumor cells has decreased significantly." (PMID 25744065, 2015). "HPV-positive tumor tissue-derived cell cultures produced much higher levels of chemokines, namely CXCL9, CXCL10, CXCL12, CCL17 and CCL21." (PMID 25949860, 2015).
tumor (continued). "The involvement of CCL21/CCR7 pair in migration and guidance of the cells detached from the primary tumor towards draining lymphatics is believed to play a significant role in the subsequent metastatic evolution of the disease." (PMID 25744065, 2015). "In this regard, it is noteworthy that prior studies characterized CCR7 and heparan sulfate as co-receptors for CCL21 accumulation on hLECs and important for recruitment of CCR7-expressing tumor cells." (PMID 24489642, 2014). "After implantation to the partially resected tumor, the gradient of local CCL21 that resulted from its sustained and localized release led to the recruitment of CD4+ T cells and CD11c+ DCs into the tumor, while tumor infiltrating Treg cells were decreased." (PMID 24810425, 2014). "In summary, factors regulating TLS formation in epithelial tissues, such as the chemokines CCL19, CCL21 and CXCL13, and the cytokine LTαβ, most likely also contribute to an anti-tumor immune response in several carcinomas/adenocarcinomas." (PMID 24762633, 2014). "The anti-tumor effectors NK and NKT cell subsets also express the CCR7 receptor and are chemo attracted by CCL21." (PMID 24810425, 2014). "Chemokines have been shown to be involved in tumor lymphangiogenesis and metastasis; for example, VEGF-C upregulated chemokine ligand 21 (CCL21) on lymphatic endothelium, whereby CCR7 expressing tumor cells were attracted towards the lymphatic vessels." (PMID 25254213, 2014). "CCL21 mediated immune response included an increased influx of CD4 and CD8 T cells and DC in the tumor, as well as increased IFN-γ, MIG-CXCL9, CXCL10, GM-CSCF and IL-12, but a concomitant decrease in immunosuppressive molecules such as PGE-2 and TGF-β." (PMID 24810425, 2014). "In immune competent mice, injection of CCL21 induced infiltration of CD4 and CD8 T cell and DC in both tumor and draining lymph nodes." (PMID 24810425, 2014). "For vaccine production, its ability to enhance IL-12p70 production, migratory response to CCL-21, APM component expression and cross-presentation of tumor antigens to T cells by DC are especially important." (PMID 23408925, 2013). "The cells of squamous cell carcinoma of head and neck secrete the chemokines CCL19 and CCL21, which leads to the activation of CCR7 and promotes tumor growth and progression." (PMID 24259307, 2013). "VEGF-C expressed by tumor cells and monocytes in the tumor stroma stimulates LEC production of CCL21, and CCL21 in turn activates its receptor CCR7 in cancer cells." (PMID 22505936, 2012). "Conversely, molecules proposed to be direct mediators of lymphatic colonization include CCL21 and SDF-1 interacting with their tumor-expressed receptors, CCR7 and CXCR4, respectively." (PMID 22295241, 2012). "We found that in comparison to controls, CCL21-vault therapy group had reduced the frequencies of Treg and MDSC and systemically enhanced T lymphocytic lysis of parental tumor cells." (PMID 21559281, 2011). "Mechanistic studies revealed that survivin-CCL21-based vaccine triggered CTL-mediated tumor cell apoptosis and significantly suppressed angiogenesis in the tumor mass." (PMID 21385454, 2011). "The migration of these two CCR7 expressing cell lines was significantly stimulated by CCL21, implying an important role and intact function of CCR7 during tumor progression." (PMID 21548969, 2011). "This fluid drainage can serve to increase metastasis both by passively carrying tumour cells and by establishing autocrine chemotactic gradients by autologously secreted heparin binding growth factors such as VEGF-A or CCL21." (PMID 20478045, 2010). "The CCR7-CCL21 chemokine axis facilitates lymphatic dissemination, as CCL21 is continuously expressed by lymphatic endothelial cells and lymph node stromal cells, directing CCR7-expressing tumor cells towards lymphatic vessels and draining lymph nodes." (PMID 41596524, 2026).